SEMA3F (semaphorin 3F)
Diseases named in the same sentence as SEMA3F in open-access papers (continued):
Sharing a sentence is not in itself a finding about the gene and the disease.
cancer (31 papers, 2008 to 2025). A tumor composed of atypical neoplastic, often pleomorphic cells that invade other tissues. "SEMA3F encodes semaphoring-3F protein involved in cell signalling, affecting cell adhesion and migration and being explored mostly in cancer therapies." (PMID 31628418, 2021). "For example, increased expression of SEMA3C associated with increased cancer cell sensitivity to Irofulven and Ibrutinib, and SEMA3F associated with Aminoflavone." (PMID 32241267, 2020). "Our findings are suggestive that SEMA3F biology is of broad relevance in many physiological and pathological conditions, including cancer and diseases associated with chronic inflammation including allograft rejection." (PMID 26156437, 2015). "SEMA3F is causally downregulated in the initiation and progression of some cancers." (PMID 29299034, 2017). "To achieve this goal, we first identified cancer cell types and assays that demonstrated SEMA3F-mediated signaling along with its anticancer effects." (PMID 41391772, 2025). "SEMA3F induces an increase in the expression of β-catenin, a member of the Wnt signalling pathway involved in the acquisition of invasive capacity in cancer cells and related to poor survival." (PMID 39138514, 2024). "Cells with higher SEMA3F expression showed higher chemosensitivity and a higher rate of cancer cell apoptosis." (PMID 39232098, 2024). "Specifically, upregulation of SEMA3B and SEMA3F following progesterone (P4) and 1,25-dihydroxyvitamin D3 treatment increases caspase-3 activity, thereby inhibiting the growth of cancer cells." (PMID 38254014, 2024). "Several studies have shown that the expression of SEMA3F and its receptors fulfill important regulatory roles in multiple forms of cancer, and that the use of treatments aimed at modifying the activity of the SEMA3F-NRP2 axis would have therapeutic potential." (PMID 35565388, 2022). "Sema3F has been reported to affect several signalling pathways in cancer cells from different histotypes." (PMID 33858502, 2021). "Nevertheless, SEMA3A, SEMA3C, and SEMA3F primarily showed up-regulated expression, and the rest of the SEMA3s mainly showed down-regulated expression in the 16 tested cancer types." (PMID 32241267, 2020). "The other major cluster is further separated into several subclusters, with one subcluster including PLXNA1, PLXNA3, and SEMA3F showing predominantly increased expression in cancer tumors." (PMID 32640719, 2020). "It was found that class 3 semaphorins (Sema3A, Sema3B, and Sema3F) decreased with the transition from in situ to invasive cancer and Sema3A expression was only significantly reduced once invasion had occurred." (PMID 31929841, 2019). "It has been reported that the SEMA3F gene is on chromosome 3p21.3 and that it is commonly deleted during cancer development." (PMID 29299034, 2017). "Semaphorin 3F (SEMA3F) is highly conserved but present at a lower level in various cancers than in healthy tissues." (PMID 29299034, 2017). "Of note, and in this context, Sema3A and Sema3F have been reported to favour the normalization of cancer vasculature and impair metastatic dissemination." (PMID 26311294, 2015). "SEMA3F also plays a pivotal role in migration and metastasis of cancer cells." (PMID 41391772, 2025). "NRP1 and NRP2 have already been implicated in cancer invasion, metastasis and progression, but this is not the case for SEMA3F, which has been traditionally considered a good prognostic marker not only for BC but also for several other types of cancer." (PMID 39138514, 2024). "Among the 7 SEMA3 gene members, expression levels of SEMA3A and SEMA3C, SEMA3C and SEMA3F showed the highest correlation across all 31 cancer types, suggesting they may share some common functions." (PMID 32241267, 2020). "Because SEMA3F suppresses rapamycin-induced Akt activation, the combination of SEMA3F with mTOR inhibitors may provide a clinical benefit in cancer therapy." (PMID 30532711, 2018).
cancer (continued). "Our finding is definitely important for studies on the development of OSCC, since it may provide new insight into the role of SEMA3F in OSCC cancer progression and be helpful in the development of further targeted drugs for OSCC cancer treatment." (PMID 29299034, 2017). "While it has been reported that SEMA3F is involved in cancer cell proliferation, migration and invasion, its function in OSCC remains unknown." (PMID 29299034, 2017). "It has been reported that SEMA3F suppressed the migration and invasion of several cancers." (PMID 29299034, 2017). "Among class 3 semaphorins, SEMA3F has been studied in several cancer types." (PMID 26447612, 2015). "Interestingly, divergent roles of SEMA3F are described in various cancer entities." (PMID 39232098, 2024). "Finally, our study revealed that SEMA3 genes, especially SEMA3C and SEMA3F may contribute to drug induced cancer cell resistance." (PMID 32241267, 2020). "We found that SEMA3B, SEMA3D, SEMA3E, and SEMA3G were all negatively associated with cancer-stem like features, but SEMA3A, SEMA3C, and SEMA3F were positively correlated with DNAss, which indicates that SEMA3s may associate with cancer cell sensitivity or resistance to chemotherapy treatment." (PMID 32241267, 2020). "We propose that targeting SEMA3F and netrin-1 may be a promising strategy for cancer therapy." (PMID 30532711, 2018). "SEMA3F, a member of class 3 SEMA family proteins, has emerged as an anticancer regulator with significant implications in cancer biology." (PMID 41391772, 2025). "Sema3E, Sema4D, and Sema7A were shown to contribute to EMT, whereas Sema3B, Sema3F, and Sema5A inhibited EMT in cancer cells." (PMID 35775491, 2022). "In contrast to SEMA3A, SEMA3C, and SEMA3F, the rest of the SEMA3 family members showed prominent down-regulation and they all negatively correlated with cancer stem-cell-like features (RNAss and DNAss) across cancer types." (PMID 32241267, 2020). "SEMA3A, SEMA3D, and SEMA3E showed relatively lower level of expression averaged across all cancer types compared to the rest of the SEMA3 family members.i.e., SEMA3B, SEMA3C, SEMA3F and SEMA3G, where SEMA3F had the highest expression." (PMID 32241267, 2020). "Among them, SEMA3F, SEMA4C, PLXNB1 and PLXNB2, involved in cancer progression and in immune system suppression, were highly expressed." (PMID 26784191, 2016). "Some semaphorins such as Sema3B and Sema3F are considered as TSG and are very often downregulated in cancer cells." (PMID 24212788, 2011). "In this scenario, our hypothesis is that SEMA3F and its receptors NRP1 and NRP2 could contribute to DCIS progression to IDC, affecting cancer epithelial cells." (PMID 39138514, 2024). "Semaphorin 3F (SEMA3F) plays a complex role in cancer progression that is not yet fully understood." (PMID 39232098, 2024).
neurodevelopmental disorder (2 papers, 2016 to 2023). A behavioral and cognitive disorder with onset during the developmental period that involves impaired or aberrant development of intellectual, motor, or social functions. "Sema3F KO mice may be served as a model to investigate the neural basis underlying some behavioral abnormalities related to the neurodevelopmental disorders." (PMID 26856818, 2016).
neoplastic disorders (1 paper, 2014). "In conclusion, in this paper we have shown that the SEMA3F/NRP2 axis is involved in thymocytes migration and as such should play a critical role in central immune regulation and in the physiopathology of neoplastic disorders of thymocytes." (PMID 25068647, 2014).
neurodegenerative disease (1 paper, 2024). A disorder of the central nervous system characterized by gradual and progressive loss of neural tissue and neurologic function. "Interestingly, SEMA3F and GRN/Progranulin are new therapeutic targets for neurodegenerative diseases and CNV." (PMID 38115754, 2024).
neurological disorders (1 paper, 2022). "Most importantly, several DEGs such as CX3CL1, SEMA3F, OPHN1, POLA2, MCM10 and POLD3 were found to be associated with neuronal/brain process and genome stability, that is known to be relevant during neurological disorders." (PMID 36267332, 2022).
vascular disorder (1 paper, 2021). A general term used to describe any disease affecting blood vessels]. "Together this work offers insight into understanding how context-dependent Sema3F modulation of endothelial responses to Vegf can be used to treat vascular disorders." (PMID 34424892, 2021).
SEMA3F also shares sentences with these, for which no sentence is quoted: oral squamous cell carcinoma (3 papers); brain malformations (2); developmental delay (2); Hearing impairment (2); infection (2); small cell lung carcinoma (2); T-cell acute lymphoblastic leukemia (2); Anosmia (1); brain cancer (1); breast (1); cleft lip (1); colorectal tumors (1); congenital hypogonadotropic hypogonadism (1); diffuse large B-cell lymphoma (1); duodenitis (1); dyslexia (1); fragile X syndrome (1); gastritis (1); heart failure (1); hypogonadotropic hypogonadism (1); invasive ductal carcinoma (1); keloid (1); leukemia (1); liver steatosis (1); megacolon (1); meningioma (1); metastatic cancer (1); multiple myeloma (1); neuroblastoma (1); Obesity (1).
A further 9 diseases each share a sentence with SEMA3F in 1 paper.